MTNR1B (melatonin receptor 1B)
Diseases named in the same sentence as MTNR1B in open-access papers (continued):
Sharing a sentence is not in itself a finding about the gene and the disease.
metabolic syndrome (5 papers, 2016 to 2023). A cluster of metabolic risk factors for CARDIOVASCULAR DISEASES and TYPE 2 DIABETES MELLITUS. "A genetic variant (C>G; rs10830963) has been described in the melatonin receptor 1B (MTNR1B) that is related to overweight and dyslipidemia, in addition to having an interaction with dietary fat and serum lipids." (PMID 35268076, 2022).
prediabetes (5 papers, 2008 to 2025). "Binary logistic regression was performed to evaluate the relationships between rs724030 in MTNR1B and prediabetes under the additive model." (PMID 39886031, 2024). "While this study primarily focuses on the analysis of MTNR1B gene variants and their associations with prediabetes risk, we acknowledge the limitation of not including variants from other genes that may also contribute to prediabetes risk." (PMID 39886031, 2024).
sleep disorder (4 papers, 2008 to 2023). A change from the patient's baseline sleeping pattern, in the hours slept and/or an alteration/dysfunction in the stages of sleep. "Mutations in the Acetylserotonin O-Methyltransferas (ASMT), Melatonin Receptor 1A (MTNR1A), and Melatonin Receptor 1B (MTNR1B) genes can induce sleep disorders in ASD patients by affecting melatonin production and utilization." (PMID 37200906, 2023). "Methylation of MTNR1B were higher in the placenta of mothers with sleep disorder (Group 1, Group 2, and Group 3) than that of the group without sleep disorder (Group 4)." (PMID 35321658, 2022). "Methylation of MTNR1B was higher and expression of MR was lower in the placenta of mothers with sleep disorder in the third trimester than in mothers without sleep disorder." (PMID 35321658, 2022).
adolescent idiopathic scoliosis (3 papers, 2011 to 2023). A scoliosis with no known cause arising in adolescent. "Recent studies also found that MTNR1B polymorphisms are associated with adolescent idiopathic scoliosis (AIS), a complex deformity of the spine that most commonly occurs in girls at the peripubertal period between 10 and 16 years of age." (PMID 21470412, 2011).
Anxiety (3 papers, 2021 to 2025). Intense feelings of nervousness, tension, or panic often arise in response to interpersonal stresses. "The astrocyte-specific knockout in Mtnr1b cKOGfap mice results in anxiety-like behavior, which is caused by down-regulation of gamma-aminobutyric acid-ergic (GABAergic) synaptic function." (PMID 40336842, 2025). "The deletion of the Mtnr1b gene, which encodes the melatonin receptor type 2 (MTNR1B), increased anxiety expression when knockout mice were tested in the OFT and EPM." (PMID 40141416, 2025). "In contrast, we observed increased anxiety-related responses (decreased time in centre and increased thigmotaxis) in female Mtnr1b KO mice." (PMID 34304635, 2021). "This provides some interesting context for our results showing that female Mtnr1b KO mice have increased anxiety levels, whereas male Mtnr1b KO mice show increased sociability." (PMID 34304635, 2021). "A recent study also reported an anxiety-like phenotype in male Mtnr1b KO mice (C3H/HeN background strain) that was limited to the light phase in one task and limited to the dark phase in another task." (PMID 34304635, 2021). "Assessment in the home-cage monitoring system revealed that female Mtnr1b KO mice have increased anxiety levels, whereas male Mtnr1b KO mice show increased sociability." (PMID 34304635, 2021). "In the context of the present study, where group-housed animals are monitored for 72 h in a low-stress home-cage environment, it is interesting to note that female Mtnr1b KO mice exhibited increased anxiety compared to males." (PMID 34304635, 2021). "Genetic deletion of the Mtnr1b gene in mice on a C3H/HeJ background also reportedly causes increased anxiety, despite the fact that mice (sex not specified) were single-housed, which can influence anxiety in mice." (PMID 34304635, 2021). "Mtnr1b KO mice were overtly normal, but showed attentional deficits, and when group housed in a low-stress environment, there was increased sociability in males and increased anxiety in female mice." (PMID 34304635, 2021). "It would be of interest to examine whether the exposure of Mtnr1b KO mice to other more stressful paradigms (such as the elevated plus-maze) would reveal sex-dependent effects on anxiety." (PMID 34304635, 2021). "For example, the function of serotonin acting at MT2/5-HT2C receptor heteromers will be perturbed in Mtnr1b KO mice, and of course 5-HT2C receptors have a well-characterised role in anxiety and sociability, and also in restraining impulsivity." (PMID 34304635, 2021). "Although these results are consistent with the anxiolytic actions of the MTNR1B agonist UCM765, the compromised locomotor activity displayed by these mice in the OFT raises concerns about the role of astrocytic MTR1B receptors in regulating anxiety states." (PMID 40141416, 2025). "Taken together, our findings of increased anxiety but not social-related behaviours in female Mtnr1b KO mice support an interaction between melatonin and oestrogen in influencing some but not all behaviours." (PMID 34304635, 2021).
atherosclerosis (3 papers, 2013 to 2023). A disease characterized by the build-up of fatty material and calcium deposition in the arterial wall resulting in partial or complete occlusion of the arterial lumen. "MTNR1B hypomethylation associated with the stenosis radiophenotype in the present study showed an epigenetic relationship with atherosclerosis development." (PMID 36658621, 2023). "The Howard University Family Study found nominal significance (p<0.05) at the SLC30A8 locus, the Multi-Ethnic Study of Atherosclerosis at MTNR1B, and the Candidate Gene Association Resource at G6PC2, GCK, and MTNR1B." (PMID 24063630, 2013). "In conclusion, the present radioepigenomic study identified and validated MTNR1B hypomethylation as an epigenetic marker to predict the presence of atherosclerosis using stenosis radiophenotypes and blood inflammatory cells." (PMID 36658621, 2023). "Although we identified MTNR1B as an epigenomic marker for atherosclerosis using stenosis radiophenotypes and blood inflammatory cells, certain limitations prevent the radioepigenomic evaluation of atherosclerosis." (PMID 36658621, 2023). "We identified and validated MTNR1B hypomethylation as an epigenetic marker to predict cranial vessel atherosclerosis using stenosis radiophenotypes and blood inflammatory cells rather than direct atherosclerotic plaque sampling." (PMID 36658621, 2023). "Different MTNR1B methylation levels between monocytes, T cells, and B cells further confirmed epigenetic remodeling in the atherosclerosis-related genes within individual inflammatory cell types of the blood." (PMID 36658621, 2023). "MTNR1B hypomethylation related to the stenosis radiophenotype may be an epigenetic marker to estimate the development of cranial vessel atherosclerosis." (PMID 36658621, 2023). "However, further studies are critical to verify the role and cell specificity of MTNR1B epigenetic alterations related to atherosclerosis development." (PMID 36658621, 2023).
autoimmune disease (3 papers, 2017 to 2025). A disorder resulting from loss of function or tissue destruction of an organ or multiple organs, arising from humoral or cellular immune responses of the individual to their own tissue constituents. "Genetic studies suggest that MTNR1B gene polymorphisms may be associated with the development of autoimmune diseases." (PMID 40332199, 2025). "However, in the past, clinical studies that explored associations of MTNRs with autoimmune diseases were limited and only focused on MTNR1B." (PMID 28961261, 2017). "Since the melatonin–MTNR1B signaling pathway affects immune regulation, autoimmune diseases, and the thyroid, its potential role in HT should be considered." (PMID 40332199, 2025). "In autoimmune diseases of multiple sclerosis (MS), there were no significant allelic associations of SNPs rs4753426 and rs10830963 in MTNR1b gene with susceptibility to MS, but the rs10830963-rs4753426 G-T haplotype associated with the risk of MS in the progressive MS group." (PMID 31815152, 2019).
depression (3 papers, 2022 to 2024). "Consistent with the PPI network, Asmt knockout may play an important role through Mtnr1b/Gna11/Plcb2/Bdnf in depression." (PMID 35771226, 2022).
idiopathic scoliosis (3 papers, 2011 to 2023). A scoliosis with no known cause. "In that study, we showed an abnormal melatonin receptor 1B expression in osteoblasts from girls with adolescent idiopathic scoliosis." (PMID 30996275, 2019). "This locus contains over 100 genes, including MTNR1B, a candidate gene for human idiopathic scoliosis." (PMID 21269476, 2011).
insomnia (3 papers, 2021 to 2025). A sleep disorder characterized by difficulty in falling asleep and/or remaining asleep. "We therefore tested if chronotype, sleep duration, insomnia, ease of awakening, daytime sleeping or daytime napping modulated the association between diurnal glucose and both the MTNR1B and CRY2 alleles." (PMID 39091879, 2024). "Our study demonstrated that insomnia affected the association between MTNR1B variants and adiposity in an African American sample population." (PMID 34020621, 2021). "Here, we hypothesized that common single nucleotide polymorphisms (SNPs) imputed in 1000 Genomes in the MTNR1B gene are associated with adiposity in African American adult men and women and that the association is modified by insomnia." (PMID 34020621, 2021). "We observed that insomnia affected the association between the MTNR1B variants and adiposity." (PMID 34020621, 2021). "This study aimed to investigate whether selected common genetic variations in the MTNR1B gene reported in previous studies were associated with adiposity in a sample of African American individuals and whether those associations were modified by insomnia." (PMID 34020621, 2021). "Additionally, insomnia modified the association between the MTNR1B variants and adiposity because we observed four novel variants (rs6483208, rs4388843, rs4601728, and rs12804291) with a significant association with adiposity when we adjusted for insomnia." (PMID 34020621, 2021). "We observed that MTNR1B and CRY2 variants showed a robust temporal association in individuals who reported insomnia, late chronotype, or short sleep." (PMID 39091879, 2024). "The selected cases include targets for the insomnia treatment: melatonin receptor 1 A (MTR1A), melatonin receptor 1B (MTR1B), orexin/hypocretin receptor type 1 (OX1R), orexin receptor type 2 (OX2R)." (PMID 41050467, 2025).
myocardial ischemia (3 papers, 2020 to 2023). A disorder of cardiac function caused by insufficient blood flow to the muscle tissue of the heart. "In case of hypoxia, MTNR1B played a protective role in preventing primary cardiomyocytes against hypoxia/reoxygenation injury caused by myocardial ischemia/reperfusion." (PMID 33525391, 2021). "In rat both MTNR1A (MT1) and MTNR1B (MT2) are expressed in myocardium, and MTNR1B was upregulated after myocardial ischemia/reperfusion in mice." (PMID 33071966, 2020).
autism spectrum disorder (2 papers, 2010). A spectrum of developmental disorders that includes autism, and Asperger syndrome. "MTNR1A and MTNR1B variants identified in 295 patients with autism spectrum disorder, 362 controls, and 284 individuals from the human genome diversity panel." (PMID 20657642, 2010).
autoimmune thyroid disease (2 papers, 2017 to 2025). Inflammatory disease of the thyroid gland due to autoimmune responses leading to lymphocytic infiltration of the gland. "Still, GWAS and other studies reported inconsistent associations between the MTNR1B locus and autoimmune thyroid diseases." (PMID 40332199, 2025). "In animals, thyroid parafollicular C-cells can synthesize melatonin, suggesting that MTNR1B gene polymorphisms may increase the risk for autoimmune thyroid diseases." (PMID 40332199, 2025). "Possible associations of single-nucleotide polymorphisms (SNPs) of melatonin receptor type 1A (MTNR1A) and 1B (MTNR1B), with autoimmune thyroid disease in an ethnic Chinese (i.e., Taiwanese) population were examined." (PMID 28961261, 2017).
delirium (2 papers, 2018 to 2022). A disorder characterized by confusion; inattentiveness; disorientation; illusions; hallucinations; agitation; and in some instances autonomic nervous system overactivity. "Genotyping for melatonin receptor 1B polymorphism was acceptable in 76 subjects of European descent of which 18 (23.7%) had delirium." (PMID 30481216, 2018). "Our preliminary retrospective study was not designed to elicit the pathophysiology of how the risk genotype of rs10830963 of the MTNR1B gene incurs an increased risk of postoperative delirium." (PMID 30481216, 2018). "Using a validated method, CHART-DEL, all charts were retrospectively reviewed and scored for the presence of delirium while blinded to the results of the melatonin receptor 1B gene polymorphism." (PMID 30481216, 2018). "Our observation suggests a role of the risk genotype, GG, of rs10830963 SNP of melatonin receptor 1B in the development of postoperative delirium." (PMID 30481216, 2018). "We hypothesized patients undergoing aortic cardiac surgery who have the risk genotype of a melatonin receptor 1B polymorphism would have a higher incidence of postoperative delirium." (PMID 30481216, 2018). "In a population of postoperative older adults, delirium status was associated with three SNPs: KIBRA SNP rs17070145, MTNR1B SNP rs10830963, and FKBP5 SNP rs1360780." (PMID 35017578, 2022). "It is possible that classifying the presence of MTNR1B genotype in participants of these trials may provide a role in understanding who may benefit from these delirium prevention therapies." (PMID 35017578, 2022). "Our results highlight the relevance of KIBRA, MTNR1B, and FKBP5 in understanding the complex relationship between delirium, cognition, and sleep, which warrant further study in larger, more diverse populations." (PMID 35017578, 2022). "Subjects without incident delirium had higher odds of having MTNR1B SNP rs10830963 CG/GG (vs. CC) genotype when compared to those with delirium in both unadjusted and adjusted models (OR 3.40; 95% CI 1.25, 9.21; p = 0.02; adjusted OR 3.88; 95% CI 1.33, 11.31; p = 0.01)." (PMID 35017578, 2022). "Those without postoperative delirium were more likely to have genotypes associated with cognitive resilience in older adults (KIBRA SNP rs17070145 CT/TT) and beneficial changes in melatonin signaling (MTNR1B SNP rs10830963 CG/GG)." (PMID 35017578, 2022). "Compared with participants with delirium, those without delirium had higher adjusted odds of KIBRA SNP rs17070145 CT/TT [vs. CC; adjusted odds ratio (aOR) 2.80, 95% confidence interval (CI) 1.03, 7.54; p = 0.04] and MTNR1B SNP rs10830963 CG/GG (vs. CC; aOR 4.14, 95% CI 1.36, 12.59; p = 0.01)." (PMID 35017578, 2022).
diabetic retinopathy (2 papers, 2013 to 2025). "Our study showed nominal associations between variants at the SLC30A8 and MTNR1B loci with any diabetic retinopathy." (PMID 24244560, 2013). "The MTNR1B single nucleotide polymorphism rs10830963 was associated with an increased risk of T2D and a decreased risk of MIC, particularly diabetic retinopathy among T2D individuals." (PMID 40869173, 2025).
Hypertension (2 papers, 2022 to 2023). The presence of chronic increased pressure in the systemic arterial system. "An earlier study also demonstrated that the MTNR1B rs10830963 G allele represented in haplotype 2 was associated with better cardiac function in patients with hypertension." (PMID 35411403, 2022). "Using a fivefold cross-validation analysis estimated with the training dataset including 70% of the 384 patients of the second patient set, lipoprotein (a), age, hypertension history, and MTNR1B methylation were identified as the top four features for the prediction model." (PMID 36658621, 2023).
melanoma (2 papers, 2017 to 2023). A malignant, usually aggressive tumor composed of atypical, neoplastic melanocytes. "To determine whether levels of MTNR1A or MTNR1B expression might be associated with disease outcome in melanoma patients, we examined publicly available expression data from TCGA." (PMID 37834395, 2023).
osteoporosis (2 papers, 2019 to 2024). A condition of reduced bone mass, with decreased cortical thickness and a decrease in the number and size of the trabeculae of cancellous bone (but normal chemical composition), resulting in increased fracture incidence. "We found specific osteoporosis-linked SNPs in genes encoding key receptors involved in bone metabolism that are classified into rhodopsin (ADRB2, CNR2, MTNR1B, FSHR, TSHR, LGR4), secretin (CALCR, GIPR), and other T7M (WLS) receptor families." (PMID 39769358, 2024). "In addition, we detected intron variants in MTNR1B, LGR4, and WLS genes that are associated with osteoporosis, increased fracture risk, and low BMD." (PMID 39769358, 2024).
prostate carcinoma (2 papers, 2022 to 2025). A carcinoma that arises from epithelial cells of the prostate gland. "Despite the lack of direct evidence, similar to our finding, a recent study demonstrated a pattern that MTNR1B rs10830963 interacted with night shift work to modify the risk of incident prostate cancer." (PMID 35411403, 2022). "For example, MTNR1B rs10830963 and HNF1B rs757210, as T2D-related genes, have inhibitory effects on prostate cancer." (PMID 40760716, 2025).
scrapie (2 papers, 2011 to 2013). A fatal disease of the nervous system in sheep and goats, characterized by pruritus, debility, and locomotor incoordination. "The gene and protein expression profiles and protein distribution of six potential genetic biomarkers (i.e., CAPN6, COL1A2, COL3A1, GALA1, MT2A and MTNR1B) are presented here for both the early and terminal stages of scrapie in five different brain regions." (PMID 23497022, 2013). "In our study, the expression of the MTNR1B gene was significantly downregulated in the Mobl, Cc and Dien regions of clinical sheep and in the Cc region of the preclinical scrapie-infected animals." (PMID 23497022, 2013). "Consequently, the decrease in MTNR1B gene expression could contribute to the brain damage observed in scrapie-affected brainstems." (PMID 21629698, 2011).